PARP1 (poly(ADP-ribose) polymerase 1)
Description:
Poly-ADP-ribosyltransferase that mediates poly-ADP-ribosylation of proteins and plays a key role in DNA repair. Mediates glutamate, aspartate, serine, histidine or tyrosine ADP-ribosylation of proteins: the ADP-D-ribosyl group of NAD(+) is transferred to the acceptor carboxyl group of target residues and further ADP-ribosyl groups are transferred to the 2'-position of the terminal adenosine moiety, building up a polymer with an average chain length of 20-30 units. Serine ADP-ribosylation of proteins constitutes the primary form of ADP-ribosylation of proteins in response to DNA damage. Specificity for the different amino acids is conferred by interacting factors, such as HPF1 and NMNAT1. Following interaction with HPF1, catalyzes serine ADP-ribosylation of target proteins; HPF1 confers serine specificity by completing the PARP1 active site. Also catalyzes tyrosine ADP-ribosylation of target proteins following interaction with HPF1. Following interaction with NMNAT1, catalyzes glutamate and aspartate ADP-ribosylation of target proteins; NMNAT1 confers glutamate and aspartate specificity (By similarity). PARP1 initiates the repair of DNA breaks: recognizes and binds DNA breaks within chromatin and recruits HPF1, licensing serine ADP-ribosylation of target proteins, such as histones (H2BS6ADPr and H3S10ADPr), thereby promoting decompaction of chromatin and the recruitment of repair factors leading to the reparation of DNA strand breaks. HPF1 initiates serine ADP-ribosylation but restricts the polymerase activity of PARP1 in order to limit the length of poly-ADP-ribose chains. In addition to base excision repair (BER) pathway, also involved in double-strand breaks (DSBs) repair: together with TIMELESS, accumulates at DNA damage sites and promotes homologous recombination repair by mediating poly-ADP-ribosylation. Mediates the poly-ADP-ribosylation of a number of proteins, including itself, APLF, CHFR, RPA1 and NFAT5. In addition to proteins, also able to ADP-ribosylate DNA: catalyzes ADP-ribosylation of DNA strand break termini containing terminal phosphates and a 2'-OH group in single- and double-stranded DNA, respectively. Required for PARP9 and DTX3L recruitment to DNA damage sites. PARP1-dependent PARP9-DTX3L-mediated ubiquitination promotes the rapid and specific recruitment of 53BP1/TP53BP1, UIMC1/RAP80, and BRCA1 to DNA damage sites. PARP1-mediated DNA repair in neurons plays a role in sleep: senses DNA damage in neurons and promotes sleep, facilitating efficient DNA repair (By similarity). In addition to DNA repair, also involved in other processes, such as transcription regulation, programmed cell death, membrane repair, adipogenesis and innate immunity. Acts as a repressor of transcription: binds to nucleosomes and modulates chromatin structure in a manner similar to histone H1, thereby altering RNA polymerase II. Acts both as a positive and negative regulator of transcription elongation, depending on the context. Acts as a positive regulator of transcription elongation by mediating poly-ADP-ribosylation of NELFE, preventing RNA-binding activity of NELFE and relieving transcription pausing. Acts as a negative regulator of transcription elongation in response to DNA damage by catalyzing poly-ADP-ribosylation of CCNT1, disrupting the phase separation activity of CCNT1 and subsequent activation of CDK9. Involved in replication fork progression following interaction with CARM1: mediates poly-ADP-ribosylation at replication forks, slowing fork progression. Poly-ADP-ribose chains generated by PARP1 also play a role in poly-ADP-ribose-dependent cell death, a process named parthanatos (By similarity). Also acts as a negative regulator of the cGAS-STING pathway. Acts by mediating poly-ADP-ribosylation of CGAS: PARP1 translocates into the cytosol following phosphorylation by PRKDC and catalyzes poly-ADP-ribosylation and inactivation of CGAS. Acts as a negative regulator of adipogenesis: catalyzes poly-ADP-ribosylation of histone H2B on 'Glu-35' (H2BE35ADPr) following interaction with NMNAT1, inhibiting phosphorylation of H2B at 'Ser-36' (H2BS36ph), thereby blocking expression of pro-adipogenetic genes (By similarity). Involved in the synthesis of ATP in the nucleus, together with NMNAT1, PARG and NUDT5. Nuclear ATP generation is required for extensive chromatin remodeling events that are energy-consuming. Plays a role in sister chromatid cohesion by mediating ADP-ribosylation of RSMC during S phase which promotes the interaction between RSMC and CDCA5/sororin, leading to enhanced interaction of CDCA5/sororin with the cohesin complex and promotion of sister chromatid cohesion. [Poly [ADP-ribose] polymerase 1, processed C-terminus]: Promotes AIFM1-mediated apoptosis. This form, which translocates into the cytoplasm following cleavage by caspase-3 (CASP3) and caspase-7 (CASP7) in response to apoptosis, is auto-poly-ADP-ribosylated and serves as a poly-ADP-ribose carrier to induce AIFM1-mediated apoptosis. [Poly [ADP-ribose] polymerase 1, processed N-terminus]: This cleavage form irreversibly binds to DNA breaks and interferes with DNA repair, promoting DNA damage-induced apoptosis.
Synonyms: PARP-1; ARTD1; ADPRT 1; ADPRT; PPOL; PARP; Poly-PARP; PARS; ADPRT1; pADPRT-1
Tractability: Small molecule: an approved drug acts on it; a structure with a bound ligand is known; a high-quality ligand is known; it has a high-quality binding pocket; it belongs to a druggable protein family. PROTAC: it is named in the literature on targeted protein degradation; UniProt records ubiquitination sites on it; ubiquitination databases record sites on it; its protein half-life has been measured; a small molecule that binds it is known.
Target class: Enzyme; Transferase
Chemical probes: AZ0108 (high quality), AZD9574 (high quality), E7449 (high quality), NMS-P118 (high quality), OLAPARIB (high quality), Saruparib (high quality), TALAZOPARIB (high quality), TALAZOPARIB, VELIPARIB (high quality), XAV939, niraparib (high quality)
Gene: Protein-coding gene on chromosome 1 (226,360,210 to 226,408,154, reverse strand). Ensembl gene ENSG00000143799.
Subcellular location: Chromosome; Nucleus; Nucleus, nucleolus; Cytoplasm, cytosol; [Poly [ADP-ribose] polymerase 1, processed N- terminus]: Chromosome; [Poly [ADP-ribose] polymerase 1, processed C- terminus]: Cytoplasm
Subcellular location (Human Protein Atlas): Nucleoplasm; Nuclear bodies; Nucleoli; Nucleoli fibrillar center
Pathways (Reactome):
DNA Repair: DNA Damage Recognition in GG-NER; Dual Incision in GG-NER; Formation of Incision Complex in GG-NER; HDR through MMEJ (alt-NHEJ); POLB-Dependent Long Patch Base Excision Repair
Disease: vRNA Synthesis
Metabolism of proteins: SUMOylation of DNA damage response and repair proteins
Signal Transduction: Downregulation of SMAD2/3:SMAD4 transcriptional activity
Gene Ontology:
Molecular function: chromatin binding; damaged DNA binding; DNA binding; enzyme activator activity; enzyme binding; identical protein binding; NAD DNA ADP-ribosyltransferase activity; NAD+ poly-ADP-ribosyltransferase activity; NAD+-histone H2BS6 serine ADP-ribosyltransferase activity; NAD+-histone H3S10 serine ADP-ribosyltransferase activity; NAD+-protein mono-ADP-ribosyltransferase activity; NAD+-protein-aspartate ADP-ribosyltransferase activity; NAD+-protein-glutamate ADP-ribosyltransferase activity; NAD+-protein-histidine ADP-ribosyltransferase activity; NAD+-protein-serine ADP-ribosyltransferase activity; NAD+-protein-tyrosine ADP-ribosyltransferase activity; non-sequence-specific DNA binding, bending; nucleosome binding; protein binding; protein homodimerization activity; protein kinase binding; RNA binding; RNA polymerase II-specific DNA-binding transcription factor binding; single-strand break-containing DNA binding; zinc ion binding; and 7 more
Biological process: apoptotic process; ATP generation from poly-ADP-D-ribose; cellular response to insulin stimulus; cellular response to oxidative stress; cellular response to UV; DNA ADP-ribosylation; DNA damage response; DNA repair; double-strand break repair; establishment of protein localization to chromatin; mitochondrial DNA metabolic process; mitochondrial DNA repair; mitochondrion organization; negative regulation of ATP biosynthetic process; negative regulation of cGAS/STING signaling pathway; negative regulation of innate immune response; negative regulation of transcription by RNA polymerase II; negative regulation of transcription elongation by RNA polymerase II; positive regulation of canonical NF-kappaB signal transduction; positive regulation of DNA-templated transcription, elongation; positive regulation of double-strand break repair via homologous recombination; positive regulation of transcription by RNA polymerase II; protein auto-ADP-ribosylation; protein localization to chromatin; protein modification process; and 33 more
Cellular component: chromatin; chromosome; chromosome, telomeric region; cytoplasm; cytosol; fibrillar center; membrane; mitochondrion; nuclear body; nuclear envelope; nuclear replication fork; nucleolus; nucleoplasm; nucleus; protein-containing complex; protein-DNA complex; site of DNA damage; site of double-strand break; transcription regulator complex
Genetic constraint (gnomAD): Loss-of-function variants: 36 observed, 104.82 expected, observed/expected ratio (o/e) 0.34, 90% interval 0.26 to 0.45. The upper end of that interval is the gene's LOEUF score, 0.45, which puts it in group 2 of 6, group 1 being the genes least tolerant of losing a copy. Missense variants: 1,046 observed, 1,241.6 expected, observed/expected ratio (o/e) 0.84, 90% interval 0.8 to 0.89. Synonymous variants: 447 observed, 466.02 expected, observed/expected ratio (o/e) 0.96, 90% interval 0.89 to 1.04.
Homologues: Orthologues: chimpanzee PARP1 (99% identical), macaque PARP1 (98% identical), pig PARP1 (95% identical), rabbit PARP1 (95% identical), dog PARP1 (94% identical), guinea pig Parp1 (93% identical), mouse Parp1 (93% identical), rat Parp1 (92% identical), tropical clawed frog parp1 (75% identical), zebrafish parp1 (71% identical), Drosophila melanogaster Parp1 (42% identical), Caenorhabditis elegans parp-1 (33% identical). Paralogues in human: PARP2 (23% identical), PARP3 (18% identical).
Diseases named in the same sentence as PARP1 in open-access papers:
PARP1 is named in the same sentence as 503 diseases in open-access papers, as found by Europe PMC text mining. Sharing a sentence is not in itself a finding about the gene and the disease. The quoted sentences say what the papers report.
breast cancer (435 papers, 2007 to 2026). A primary or metastatic malignant neoplasm involving the breast. "PARP1 inhibitors are FDA-approved for BRCA1/2-mutated breast cancer but show limited efficacy in wild-type cancers and face resistance issues." (PMID 41693691, 2026). "Incorporation of computational chemistry has revolutionized the drug development paradigm for PARP1 inhibitors, allowing for unmatched accuracy and efficacy in designing therapies for breast cancer, particularly in BRCA1/2-mutated tumors." (PMID 41304924, 2025). "A LASSO Cox regression model incorporating PRMT1, PARP1, P65, and IL-1B indicates that these molecules are linked to poor prognosis in breast cancer, confirmed by the GSE6532 dataset." (PMID 40927753, 2025). "Two PARP1 mutations (E90K and S104R) found in breast cancer enhance the interaction between PARP1 and USP15 and inhibit PARP1 ubiquitination, leading to abnormally elevated PARP1 levels." (PMID 40904702, 2025). "The SNP rs1805414 is characterised by a C‐to‐A substitution at cDNA position 852 within exon 7 of PARP1 and has been associated with an increased risk of breast cancer but a decreased risk of colorectal cancer." (PMID 40833230, 2025). "Emerging evidence authenticated that ADP-ribosylated DDX21 caused by snoRNA-activated PARP-1 accelerated rDNA transcription, ribosome biogenesis, and protein translation, leading to the increased growth of breast cancer cells." (PMID 39866844, 2025). "This phenomenon, called synthetic lethality, prompted clinical trials in which PARP-1 inhibitors were used as monotherapy in patients with germline BRCA-mutated ovarian or breast cancers." (PMID 39858519, 2025). "The role of PARP1 in breast cancer is preeminent in BRCA1/2 mutations that impair homologous recombination repair (HRR) and make cells reliant on PARP1-catalyzed base excision repair (BER) for existence." (PMID 41304924, 2025). "PARP1 is significantly amplified and highly expressed in recurrent breast cancer, while PTEN loss has been linked to an increased risk of breast cancer, and AIFM1 plays a crucial role in tumor invasion and metastasis by inactivating PTEN." (PMID 40564403, 2025). "In breast cancer patients who underwent surgery, patients with high PARP-1 expression demonstrated a four-fold higher risk of developing distant metastasis." (PMID 39201718, 2024). "For BRCA mutation-related breast cancer, PARP1 inhibitors such as Olaparib are widely used in clinical treatment." (PMID 39342122, 2024). "The results showed that the risk of mammary cancer metastasis in the high PARP1 expression group was 4.092 times that in the low PARP1 expression group (RR = 4.092, 95% CI 2.475–6.766, P < 0.001)." (PMID 38388665, 2024). "PARP1 is thus a validated therapeutic target for ovarian and/or breast cancer with deleterious BRCA mutations." (PMID 38582911, 2024). "Small-molecule PARP1 inhibitors have become the standard of care for women with metastatic ovarian cancer and breast cancer harbouring the single or double BRCA1 and BRCA2 mutations." (PMID 38582911, 2024). "Compared to mice with single deficiencies in T cell PARP1 or PARP2, mice with PARP1/2 double deficiencies have faster proliferating breast cancer cells and reduced CD4+ and CD8+ T cell infiltration in tumor tissues." (PMID 38111536, 2023). "The survival benefit of PARP1 inhibitor in BRCA1-deficient breast cancer proved that the DNA repair pathway is a promising target for cancer treatment." (PMID 37968256, 2023). "We identified the gene PARP1 with the second highest degree in the mutation driver module for breast cancer." (PMID 36266635, 2022). "The aim of the study was the determination of PARP-1 expression in the context of the presence of BRCA1 mutations in circulating tumor cells of breast cancer patients." (PMID 35406503, 2022). "PARP1 has been reported to be overexpressed and to be associated with poor overall survival of breast cancer patients 70,71." (PMID 35739271, 2022).
breast cancer (continued). "The E3 ubiquitin ligase MDM2 ligand nutlin-3 derivative and poly (ADP) ribose polymerase 1 (PARP1) ligand niraparib derivative PROTACs were used to target PARP1 degradation, thus causing human breast cancer cells MDA-MB-231 to undergo apoptosis." (PMID 36142231, 2022). "For example, loss of 53BP1 or components of the non‐homologous end‐joining pathway can suppress the synthetic lethal interaction between poly (ADP‐ribose) polymerase 1 (PARP1) and the breast cancer susceptibility gene BRCA1." (PMID 34706158, 2022). "And PARP1 is a hub gene with the second-highest degree in the mutation driver module for breast cancer." (PMID 36266635, 2022). "The nuclear protein Poly (ADP-ribose)-Polymerase 1 (PARP1) is a suitable target against which few inhibitors (PARPi) are clinically approved for treatment of breast cancer with germline BRCA mutation (BRCAmut)." (PMID 36104637, 2022). "Inhibitors of poly (ADP-ribose) polymerase 1 (PARP1) have shown promise for targeting cancer cells harboring mutations in the double-strand break (DSB) repair breast cancer genes, BRCA1 and BRCA2, where these drugs induce synthetic lethality." (PMID 34149432, 2021). "Inhibitors of PARP1 are already investigated due to their synthetic lethal effects with the combination of pre-existing BRCA1/2 (Breast Cancer gene 1/2) loss-of-function mutations." (PMID 33562002, 2021). "PARP-1 is associated with a poor outcome in breast cancer and was markedly upregulated in the MCS, but treatment with a PARP-1 inhibitor did not interfere with MCS formation." (PMID 35052703, 2021). "Genome-wide association studies in breast cancer cell lines showed that PARP1 correlates with other epigenetic elements such as active histone marks." (PMID 33804735, 2021). "We have demonstrated that rs1805414, a human PARP1-SNP, is associated with higher levels of mRNA levels than the WT or heterogeneous genotype, in a cohort of 415 breast cancer patients from the TCGA." (PMID 32352035, 2020). "Depletion of KLF4 by RNA interference or interference with PARP1 function by KLF4YYR/AAA (a PARylation‐deficient mutant) significantly sensitizes breast cancer cells to PARP inhibitors." (PMID 33231937, 2020). "For example, poly ADP-ribose polymerase 1 (PARP1) is involved in multiple DNA repair pathways to maintain genomic stability so PARP1 inhibitors have been approved to treat ovarian cancer, breast cancer, and other DNA repair-deficient tumors." (PMID 33304656, 2020). "PARP1 inhibitors enhance the effects of DNA damaging drugs in homologous recombination-deficient tumors including tumors with breast cancer susceptibility gene (BRCA1) mutation." (PMID 32405340, 2020). "Inhibition of BRCA1 and BRCA2 expression by FR suggested a synergistic cytotoxic effect with olaparib based on the fact that this PARP1 inhibitor is effective in breast cancer with genetic deficiencies in BRCA1 or BRCA2." (PMID 30719229, 2019). "Since these features apply to many functionally linked genes, the role of PARP1 in defining the breast cancer phenotype at the transcription level is likely to go far beyond cell cycle progression and the removal of DNA damage." (PMID 31614656, 2019). "Inactivation of BRCA1 (breast cancer and ovarian cancer-specific tumor suppressor protein) by mutations or promoter methylation has been shown to be associated with upregulated PARP1." (PMID 31856867, 2019).